EGFR (epidermal growth factor receptor)
Diseases named in the same sentence as EGFR in open-access papers (continued):
Sharing a sentence is not in itself a finding about the gene and the disease.
adenocarcinoma (continued). "Regarding targetable molecular alterations, adenocarcinomas with STAS have been related to wild type epidermal growth factor receptor (EGFR), ALK rearrangement and Kirsten rat sarcoma viral oncogene homolog (KRAS) mutation." (PMID 32564261, 2020). "Ten patients had epidermal growth factor receptor (EGFR)-mutated and one had anaplastic lymphoma kinase (ALK)-rearrangement adenocarcinomas." (PMID 33228799, 2020). "In our research, a comutation of EGFR 19 del with GOPC‐ROS1 rearrangement was detected in a 60‐year‐old smoking male with an adenocarcinoma." (PMID 32729257, 2020). "Most previous studies have shown higher EGFR expression in squamous cell morphology compared to adenocarcinoma, although others have shown opposite results." (PMID 33247670, 2020). "The germline T790M EGFR mutation is present in approximately 1% of NSCLC cases with a median age at diagnosis of 40 years, and the most common histology is adenocarcinoma." (PMID 32104210, 2020). "Nodule type differed significantly between the KRAS and EGFR groups (P = 0.035), and all KRAS mutation adenocarcinomas were solid nodules." (PMID 31783917, 2019). "Women with adenocarcinoma also had lower comorbidity burden, less advanced stage, and were more often EGFR positive." (PMID 31247015, 2019). "The RB1 alteration in this patient was found on repeat biopsy at the time of progression on first generation EGFR tyrosine kinase inhibitor (TKI), along with an acquired EGFR T790M mutation and a histopathology of adenocarcinoma." (PMID 30773851, 2019). "AGR2 has been shown to stimulate the expression of the EGF receptor (EGFR) ligand amphiregulin (AREG) in adenocarcinoma cells." (PMID 31434729, 2019). "Adenocarcinoma that has spread can occur due to a mutation in the genes of Kirsten rat sarcoma viral oncogene homolog (K-RAS), epidermal growth factor receptor (EGFR), and anaplastic lymphoma kinase (ALK)." (PMID 30956908, 2019). "Further studies are warranted to validate these in a larger patient cohort and identify further markers of interest such as ROS1 and RET rearrangements, other EGFR mutants and in NRAS-, KRAS-mutated adenocarcinomas." (PMID 30889898, 2019). "From the initial 13,818 patients with advanced adenocarcinoma, we excluded those who were EGFR(-) but received EGFR-TKI as first-line therapy (n = 771), and those who were ECOG equal to 5 points (n = 4)." (PMID 31419239, 2019). "In the subgroup of patients with wild-type EGFR adenocarcinoma, the median OS of patients with TTF-1 positive expression was significantly longer compared to those with TTF-1 negative expression (13.6 months vs. 5.8 months, p = 0.005)." (PMID 31196060, 2019). "To eliminate the impact of SSN on DESCT quantitative parameters, and since the KRAS mutation adenocarcinoma are all SN as well, we deleted imaging data of SSN and then compared the difference between the two groups (KRAS n = 12 to EGFR n = 44)." (PMID 31783917, 2019). "Resistance mechanisms that bypass EGFR signaling, such as MET and HER2 amplification account for another 15%-20% of resistance to EGFR inhibitors and a less common mechanism is the histological transformation of EGFR-mutant adenocarcinoma to SCLC." (PMID 35582592, 2019). "In conclusion, the SN proportion was higher with KRAS than EGFR mutations and all KRAS mutation adenocarcinomas were SN tumors." (PMID 31783917, 2019). "EGFR and KRAS mutations were more frequently observed in adenocarcinomas (10.2% vs. 0%, P = 0.042; 35.6% vs. 5.3%, P = 0.001 respectively)." (PMID 31668020, 2019). "In the subgroup of wild-type EGFR adenocarcinoma patients, TTF-1 positivity was also a good prognostic indicator for OS and progression-free survival (PFS) after first-line cytotoxic chemotherapy." (PMID 31196060, 2019).
adenocarcinoma (continued). "EGFR mutant adenocarcinomas with distinctive clinicopathologic features, especially solid histologic pattern and higher stage showed higher PD-L1 expression." (PMID 31561631, 2019). "To further support our findings, we assessed the mRNA expression of MAP17 and EGFR in different adenocarcinoma PDXs and treated them with erlotinib." (PMID 30119639, 2018). "The same group reported increased binding (factor 5) of an iodinated anti-EGFR antibody to cryosections of HNSCC compared to adenocarcinomas and normal mucosa." (PMID 29989001, 2018). "Results of the present in vitro study, including initial microarray analyses, demonstrate that MMP-1 expression is more significantly increased in EGFR-TKI–resistant adenocarcinoma cells than in EGFR-TKI–sensitive cells." (PMID 29463039, 2018). "In adenocarcinoma patients, EGFR–TKI objective response rates, OS, and PFS are 66–74%, 19–21 months, and 9.4–10 months versus 25–27%, 13.48 months, and 3–5 months for SQCC, respectively." (PMID 30087852, 2018). "We provide evidence of synergy between EGFR and TrkB inhibitors in the vast majority of adenocarcinoma cell lines, and in two SCC cell lines." (PMID 29581842, 2018). "EGFR mutations are more commonly observed in patients with light or no smoking history, female patients, adenocarcinomas or NSCLC with an adenocarcinoma component." (PMID 29914100, 2018). "The clinicopathological characteristics of EGFR-mutated and KRAS-mutated adenosquamous cancers is comparable to those observed for their adenocarcinoma counterpart." (PMID 30060526, 2018). "About 5% of patients suffered from transformation from EGFR-mutant adenocarcinoma to small-cell lung cancer (SCLC) after acquired resistance to EGFR TKIs." (PMID 29455650, 2018). "SCLC transformation arises from common progenitor cells of adenocarcinoma in response to EGFR TKI therapy." (PMID 29455650, 2018). "Driver genetic mutations, including EGFR, KRAS, and BRAF, are thought to be associated with the initiation and progression of adenocarcinoma as described in this review." (PMID 29690599, 2018). "The tet‐on driven transgenic EGFR L858R mutant expression in Clara cells of the C57BL/6NTG(EGFR L858R) × TG(CC10‐RTTA) mice resulted in adenocarcinoma formation throughout the lung." (PMID 30220105, 2018). "Adenocarcinoma with the wild-type epidermal growth factor receptor (EGFR) gene accounted for 69% (42/61) of all patients, and phase III and IV disease accounted for 81.2% (121/149) of all patients." (PMID 30257820, 2018). "This is significant because ALK rearranged adenocarcinomas are resistant to the commonly used EGFR kinase inhibitors." (PMID 30546837, 2018). "To confirm these results, we analysed data concerning adenocarcinoma cell line sensitivity to different EGFR inhibitors from the GDSC database." (PMID 30119639, 2018). "The 5.3% frequency of exon 14 MET mutations was derived from 150 adenocarcinomas carrying similar mean gene mutation frequencies as those previously reported in France for KRAS (23.3%), EGFR (9.3%), and BRAF (0.3%)." (PMID 28418914, 2017). "The EGFR mutation rate was 34.9% and 42.3% among patients with NSCLC and adenocarcinoma, respectively." (PMID 28107191, 2017). "Somatic epidermal growth factor receptor (EGFR) mutations are present in around 50% of Asian patients and in 10–15% of Caucasian patients with metastatic non-small cell lung cancer (NSCLC) of adenocarcinoma histology." (PMID 28560182, 2017). "Subsequently, the pathological analysis of a bronchoscopy specimen led to a diagnosis of adenocarcinoma harboring an EGFR exon 19 deletion." (PMID 29169381, 2017). "A higher EGFR mutation rate was identified in TTF-1+ adenocarcinomas, but a fraction of TTF-1− adenocarcinomas still had EGFR mutation." (PMID 29296178, 2017). "A549 cells are EGFR wild type adenocarcinoma cells, while H1975 (EGFR L858R + T790M) and HCC827 (EGFR E716-A750del) cells are EGFR mutant adenocarcinoma cells." (PMID 29170453, 2017).
adenocarcinoma (continued). "We then performed subgroup Kaplan-Meier analyses using only data from patients who had 1) ECOG status 0 or 1, 2) adenocarcinoma histology, 3) TKI-sensitizing EGFR mutations, 4) gefitinib and/or erlotinib treatment or 5) first-line treatment with TKIs." (PMID 28467813, 2017). "Further, several genes associated with glucose metabolism or the cell cycle were specifically down-regulated in EGFR m+ adenocarcinomas." (PMID 28422979, 2017). "HCC827 (EGFR E746-A750 deletion) and A549 (EGFR wild-type) are adenocarcinomas, whereas H520, an EGFR-negative cell line, is a squamous carcinoma of the lung." (PMID 28787001, 2017). "A total of 152 patients with metastatic EGFR-mutant adenocarcinoma with BM who were diagnosed and received icotinib therapy between October 2011 and October 2014 were identified." (PMID 28332624, 2017). "In this report we show that induction of YAP is a possible mechanism of drug resistance to EGFR tyrosine kinase inhibitors in NSCLC adenocarcinomas, and that inhibiting this co-transcription factor can re-sensitize the cells to EGFR inhibitors." (PMID 28680534, 2017). "In total, 66 EGFR-mutant patients with stage IV adenocarcinoma were eligible, of whom 51 underwent re-biopsy upon initial progression." (PMID 27999211, 2017). "In conclusion, radiomic features enable PFS estimation in EGFR-mutant adenocarcinoma patients treated with first-line EGFR TKIs." (PMID 29099855, 2017). "GO term analysis revealed that the glucose metabolism-related and the cell cycle-related genes were enriched among the down-regulated genes in EGFR m+ adenocarcinomas, which supports our results for 18F-FDG PET, with lower levels of SUVmax." (PMID 28422979, 2017). "Radiomic features enable PFS estimation in EGFR mutant adenocarcinoma patients treated with first-line EGFR TKIs." (PMID 29099855, 2017). "Several genes associated with glucose metabolism or the cell cycle were specifically down-regulated in EGFR m+ adenocarcinomas." (PMID 28422979, 2017). "Consistent with a previous report, PD-L1 levels were higher in tumors with SCC histology than in adenocarcinomas and lower in mutant EGFR than in wild-type EGFR carriers." (PMID 29152077, 2017). "Somatic EGFR mutations are present in around 50% of patients in Asia and in 10–15% of Caucasian patients with metastatic NSCLC with adenocarcinoma histology." (PMID 28560182, 2017). "We also analyzed correlations between CCDC106 expression and driver mutations, such as EGFR and KRAS, in adenocarcinoma tissues." (PMID 28460455, 2017). "AIS and adenocarcinoma showed strong expression of a single RTK (EGFR, HER2 or c-Met) on the cell membrane in 41 (77.4%) of 53 cases." (PMID 28859123, 2017). "Higher serum CEA level has been associated with higher EGFR mutation rate, higher disease control rate (DCR) and longer survival time in advanced adenocarcinoma patients treated with EGFR-TKI." (PMID 27072585, 2016).
adenocarcinoma (continued). "Two weeks later, he received bronchoscopy, and the result showed small-cell lung cancer (SCLC) mixed with an adenocarcinoma harbouring an EGFR exon 19 deletion." (PMID 27533086, 2016). "When stratified by histology, the frequency of EGFR testing ranged from 2.7% among large cell tumors to 20.8% among adenocarcinomas." (PMID 27294665, 2016). "In the subgroup of 161 patients with adenocarcinoma, we compared the pathological subtypes based on the 2011IASLC/ATS/ERS classification among the three EGFR mutation groups." (PMID 27527915, 2016). "Among patients with stage IV adenocarcinomas, EGFR testing remained significantly more likely among Hispanics, patients with private/military/other insurance and patients with no comorbidities." (PMID 27294665, 2016). "We observed a direct relationship between high CEA and unfavorable prognosis, but only for adenocarcinoma patients with wild-type EGFR." (PMID 27072585, 2016). "In EGFR wild-type adenocarcinoma, the proportion of EML4-ALK translocation was 9.8% and predominant in patients younger than 65 years (14% versus 3.4%)." (PMID 27191886, 2016). "To verify the in vitro results of negative correlation between MIIP and EGFR protein expression, we evaluated the expression level of MIIP and EGFR protein in 28 pairs of clinical adenocarcinoma NSCLC specimens by immunohistochemistry." (PMID 26824318, 2016). "CEA levels (P < 0.001 for DFS; P = 0.002 for OS) and clinical stage were independently predictive and prognostic in EGFR wild-type adenocarcinoma patients." (PMID 27072585, 2016). "The remaining 348 adenocarcinoma patients were EGFR wild-type and CEA, Cyfra21-1, and NSE elevated in 123, 113, and 85 patients, respectively." (PMID 27072585, 2016). "Epidermal growth factor receptor (EGFR) is the most common driver mutation in NSCLC, specifically adenocarcinomas." (PMID 29282427, 2016). "Further stratification analysis revealed that in EGFR exon 19 deletion adenocarcinomas, elevated Cyfra21-1 was an independent prognostic factor (P = 0.002)." (PMID 27072585, 2016). "Spearman's correlation analysis demonstrated that the immunoreactivity score of MIIP was significantly inversely correlated with that of EGFR in adenocarcinoma NSCLC specimens." (PMID 26824318, 2016). "Clinicopathological characteristics of a 54 year old female patient who had ALK rearrangements and EGFR wild type was smoker, adenocarcinoma histology and presence of metastasis." (PMID 27217997, 2016). "Previous reports mostly demonstrated ALK rearrangement frequencies of 3-5 % in unselected patient populations, 3–25 % in adenocarcinomas, and 33 % in highly selected patient populations (EGFR wild-type, female, non/light smokers)." (PMID 27495736, 2016). "The frequency and clinicopathological characteristics of EGFR and K-Ras mutations in ASC are similar to those of Asian patients with adenocarcinomas." (PMID 26923333, 2016). "They identified 17 microRNAs that were differentially expressed between EGFR-mutant and EGFR-wild-type adenocarcinomas, and three microRNAs differentially expressed between KRAS-mutant and KRAS-wild-type adenocarcinomas." (PMID 27005669, 2016). "For EGFR wild-type adenocarcinoma patients, CEA (HR = 2.150, P < 0.001 for DFS; HR = 1.711, P = 0.002 for OS) and clinical stage (HR = 1.527, P = 0.020 for DFS; HR = 1.593, P = 0.026 for OS) were independently predictive and prognostic." (PMID 27072585, 2016). "In summary, the results from the present study demonstrate that high EGFR expression is an unfavourable prognostic factor in in gemcitabine treated pancreatobiliary type adenocarcinoma." (PMID 27070783, 2016). "Cox proportional hazards analysis of the impact of EGFR expression on recurrence-free and overall survival in strata according to adjuvant gemcitabine in patients with PB-type adenocarcinoma." (PMID 27070783, 2016).
adenocarcinoma (continued). "Further stratification analysis revealed that Cyfra21-1 (HR = 2.713, P = 0.002) was an independent prognostic factor for EGFR del19 adenocarcinoma patients." (PMID 27072585, 2016). "An anti-PD-1 antibody significantly reduces tumor growth and prolongs the survival of mice with EGFR-mutant adenocarcinoma." (PMID 26175921, 2015). "Our study shows, for the first time, that the upregulation of GAS5 can overcome the resistance of human adenocarcinoma cells to EGFR-TKIs, at least partially by downregulating IGF-1R." (PMID 25925741, 2015). "EGFR mutations and HER2 overexpression have been shown to be prevalent in NSCLC tumors, particularly adenocarcinomas (Bonanno, Favaretto, Rugge, Taron, & Rosell, 2011)." (PMID 27069737, 2015). "Although the presence of two different histological components in AdSqLCs, identical mut-EGFR have been detected simultaneously in both components, suggesting that the adenocarcinoma and squamous cell carcinoma have a possible clonal origin." (PMID 26422230, 2015). "Our data suggest that combination therapy of β-catenin pathway-targeting drugs and EGFR-TKIs will be effective for adenocarcinoma patients with primary or acquired resistant to EGFR-TKIs." (PMID 26268703, 2015). "The presence of EGFR mutations defines a specific molecular subgroup of NSCLC (~15% of Caucasian patients with adenocarcinomas) that respond to an EGFR TKI in over 60% of patients." (PMID 26308162, 2015). "EGFR mutant NSCLC is now classified as an independent subtype with its own therapies and as such all adenocarcinomas should be tested routinely to screen for mutations." (PMID 26371045, 2015). "Several studies reported that mut-EGFR and ALK-R, generally mutually exclusive, are frequently associated with specific histological features within the framework of adenocarcinomas." (PMID 26422230, 2015). "The mutant EGFR in adenocarcinoma lung cancer is approximately 10% in United States and 30~50% in Asia." (PMID 26609535, 2015). "In contrast, KRAS mutations, despite ostensibly functioning just downstream of EGFR, tend to occur in adenocarcinomas with mucinous histology from male smokers." (PMID 26556242, 2015). "K-Ras and EGFR mutations were mutually exclusive (P=0.0006), observed only in the NSCLC patients with adenocarcinoma (P<0.0001)." (PMID 25436007, 2015). "We undertook a single-institution retrospective analysis of 93 consecutive patients with stage IV NSCLC adenocarcinoma with known KRAS and EGFR MT status to determine the association of KRAS MT with survival." (PMID 26471290, 2015). "Our studies identify EGFR as an oncogenic driver that initiates and maintains the neoplastic process in our mouse model, and is activated in human adenocarcinomas of the middle ear and ELSTs." (PMID 26027747, 2015). "Ten of 14 adenocarcinomas underwent molecular mutational profiling: 2/8 had KRAS mutation, 1/10 had EGFR mutation, and 0/5 had ALK rearrangement." (PMID 25689302, 2015). "EGFR mutations are frequently found in the early stages of nGGO, such as in AAH and AIS, and play an important role in the pathogenesis of adenocarcinoma with GGO patterns." (PMID 24885886, 2014). "The discovery of a mutation on the epidermal growth factor receptor (EGFR) gene made a huge difference in the treatment strategy for NSCLC, especially adenocarcinoma." (PMID 25563355, 2014). "We discuss a case of a 67-year-old Caucasian man, a former heavy cigarette smoker, with a diagnosis of wild-type epidermal growth factor receptor locally advanced adenocarcinoma." (PMID 24661457, 2014). "The HCC4006 adenocarcinoma cell line has an EGFR deletion in exon 19 and EGFR amplification with the copy number 5.2, and shows half maximal inhibitory concentration (IC50) of Gefitinib at 0.25 μM." (PMID 25375092, 2014). "Here, we describe a complete response to erlotinib treatment in a male former heavy cigarette smoker with wild-type EGFR adenocarcinoma." (PMID 24661457, 2014).